ATP6AP1 (ATPase H+ transporting accessory protein 1)
Diseases named in the same sentence as ATP6AP1 in open-access papers (continued):
Sharing a sentence is not in itself a finding about the gene and the disease.
tuberculosis (1 paper, 2022). A chronic, recurrent infection caused by the bacterium Mycobacterium tuberculosis. "ATPase H+ transporters, including ATP6AP1, ATP6V0B, and ATP6V0D1, were identified in the other module-related pathways such as lysosome, tuberculosis, and phagosome." (PMID 36034872, 2022).
viral infection (1 paper, 2024). "In addition, they report the interaction of two subunits, ATP6AP1 and ATP6V1A, with SARS-CoV-2 non-structural protein 6 and membrane protein, suggesting a direct involvement of V-ATPase members in viral infection." (PMID 38674105, 2024).
tumor (18 papers, 2016 to 2025). "Our study revealed the potential role of ATP6AP1 played in regulating tumor immunity and activating tumor-associated pathways based on bioinformatic analysis." (PMID 38369634, 2024). "Nevertheless, ATP6AP1’s underlying activities and mechanisms in tumor growth and immunology remain partially characterized." (PMID 36147483, 2022). "We analyzed the association between ATP6AP1 expression and tumor immunity using the ESTIMATE algorithm and single-sample GSEA (ssGSEA)." (PMID 36147483, 2022). "We also investigated tumor-immune infiltration and its association with the prognostic value of ATP6AP1 in BC." (PMID 34228637, 2021). "ATP6AP1 was associated with tumor immune cell infiltration and immune checkpoint expression in CRC." (PMID 38369634, 2024). "Tumor tissues expressing high levels of ATP6AP1 may be particularly susceptible to viral interference." (PMID 34228637, 2021). "The high expression of ATP6AP1 is strongly correlated with advanced tumor stage, poor prognosis and immune microenvironment changes." (PMID 40281381, 2025). "This comprehensive investigation delineates the molecular landscape of pyroptosis-related mechanisms in HCC pathogenesis, particularly highlighting ATP6AP1-mediated tumor microenvironment remodeling as a novel therapeutic target." (PMID 40281381, 2025). "Based on the TCGA database, we conducted ATP6AP1 single gene analysis, divided the tumor samples into ATP6AP1 low expression group and ATP6AP1 high expression group by R (version 4.1.1), and screened differentially expressed genes." (PMID 38369634, 2024). "CRC tissue microassays confirmed that ATP6AP1 was highly expressed in tumor tissues, and high-level ATP6AP1 predicted a poor prognosis." (PMID 38369634, 2024). "Among 7 genes, ATP6AP1 (ATPase H+ Transporting Accessory Protein 1) showed a consistent upregulation in tumor tissues across multiple cohorts and TCGA cohort." (PMID 39627767, 2024). "First, we analyzed the transcription levels of ATP6AP1 across various cancers by comparing tumor and normal samples using data from the TCGA database." (PMID 38369634, 2024). "Compared with the results of the TCGA database, only the COA6 and ATP6AP1 expressions were significantly different between LIHC tumor tissues and normal tissues from the GEPIA2 database." (PMID 36313717, 2022). "We subsequently determined the correlations between the levels of diverse immune cell markers and ATP6AP1, while removing the influence of tumor purity." (PMID 34228637, 2021). "Correlation analyses revealed that ATP6AP1 levels correlated remarkably with tumor purity and to varying degrees with immune cell levels." (PMID 34228637, 2021). "The positive correlation of ATP6AP1 levels with CD4+ Treg and macrophage levels further explains why patients with higher ATP6AP1 levels had poorer prognoses, since these TIICs can promote tumor growth." (PMID 34228637, 2021). "Next, we used the Tumor-Immune System Interaction Database (TISIDB) to further assess the relationship between ATP6AP1 levels and TIIC levels in BC." (PMID 34228637, 2021). "Notably, ATP6AP1 mRNA and protein levels were significantly upregulated in tumor tissues, strongly correlating with TNM staging." (PMID 40281381, 2025). "High ATP6AP1 expression accounted for a higher proportion in tumor tissues." (PMID 38369634, 2024). "ATP6AP1 expression was remarkably increased in tumor tissues compared with normal tissues of CRC." (PMID 38369634, 2024). "ATP6AP1 might be an indicator of the inhibition of the immune response to cancer cells and the promotion of iron metabolism for tumor progression." (PMID 36147483, 2022). "Since ATP6AP1 levels correlated negatively with CD8+ T cell and B cell levels in the present study, high ATP6AP1 expression in BC tissues may inhibit the cytotoxic response to tumor cells, resulting in poor outcomes." (PMID 34228637, 2021).
tumor (continued). "We then investigated whether ATP6AP1 expression correlated with the levels of TIICs and immune cell markers in BC through Tumor Immune Estimation Resource (TIMER)." (PMID 34228637, 2021). "Data from the Tumor Immune Estimation Resource, Tumor-Immune System Interaction Database and Kaplan-Meier plotter indicated that ATP6AP1 expression correlated with immune infiltration, and that its prognostic effects in BC depended on tumor-infiltrating immune cell subtype levels." (PMID 34228637, 2021). "The genes encoding CCDC115, ATP6AP1, and ATP6AP2 may play a tumor suppressor role in different cancer types." (PMID 33680927, 2020). "Thus, ATP6AP1 may influence tumor progression through different mechanisms depending on the cancer type." (PMID 40133274, 2025). "The high expression levels of RAB7A, PIK3C3, ATP6AP1, ATP6V1A, CCDC22, and NPC1 were significantly associated with lower tumor purity of patients with hematologic cancer LAML, while TMPRSS2, PIK3C3, ATP6AP1, and ATP6V1A expressions were obviously correlated with higher tumor purity of KICH patients." (PMID 35082790, 2021). "In light of the high frequency of ATP6AP1 and ATP6AP2 inactivating mutations in GCTs, which suggests a putative tumor suppressor role for these genes, we hypothesized that their loss of function would result in the acquisition of oncogenic properties in vitro in GCT-relevant cell models." (PMID 30166553, 2018). "Several glycoproteins associated with the lysosomal pathway, including LAMP1, ASAH1, ATP6AP1, and HEXA, exhibited significantly increased levels of specific glycoforms bearing high-mannose glycans in tumor tissue." (PMID 41061966, 2025). "Compared to the control group, ATP6AP1 overexpression drastically increased the tumor volume and weight, moreover, ATP6AP1 overexpression reduced sensitivity to TAM-mediated tumor growth inhibition." (PMID 40133274, 2025). "To enhance our insights into the prognostic validity of the five-gene signature, we examined the expression of ATP6AP1, SLC7A5, EPDR1, SDC1, and PIGR in 13 paired BC samples, comparing them with their adjacent non-tumor tissues through RT-PCR." (PMID 38162504, 2023). "Then ATP6AP1, PSMD14 and HSP90AB1 were selected to verify the expression in 63 cases of tumor tissues and the adjacent non-tumor tissues." (PMID 38327651, 2023). "Then, we analyzed the relapse-free survival rate (RFS) of abnormal expression of ATP6AP1, PSMD14 and HSP90AB1 in these 63 HCC tissues and paired non-tumor tissues through five years of follow-up and in the K-M plotter database." (PMID 38327651, 2023). "In this study, we validated the high expression of ATP6AP1, PSMD14 and HSP90AB1 in HCC tissue and the aberrant expression of PSMD14 in tumor tissue related to the poor prognosis." (PMID 38327651, 2023). "We detected significant downregulation of IRS2 and NT5E in tumor tissues, whereas CACNA1H, CHPF, SDC1 and ATP6AP1 were highly expressed in tumor tissues than in normal tissues." (PMID 36277284, 2022). "We found that ATP6AP1 and CEP112 had an overall positive correlation with the expression of tumor-infiltrating immune cells, while the five other modeling genes showed the opposite trend." (PMID 36552760, 2022). "Finally, ATP6AP1, PSMD14 and HSP90AB1 were chosen to validate the expressions in 63 cases of HCC tissues and the corresponding adjacent non-tumor tissues." (PMID 38327651, 2023). "According to the results, ATP6AP1, PSMD14 and HSP90AB1, which are generally highly expressed in HCC tissue, were chosen and verified the expressions in 63 cases of HCC tissues and the paired adjacent non-tumor tissues." (PMID 38327651, 2023). "The results showed that ATP6AP1, PSMD14, HSP90AB1 were generally highly expressed in tumor tissues." (PMID 38327651, 2023). "We identified ATP6AP1, PSMD14 and HSP90AB1, which were exactly highly expressed in tumor tissue." (PMID 38327651, 2023).
tumor (continued). "Our analysis indicated that ATP6AP1 expression in certain cell types may be reduced after SARS-CoV-2 infections; thus, its expression in tumor tissues may also be reduced following such infections." (PMID 34228637, 2021). "Further analysis implied that the level of ATP6AP1 is not correlated with CRC malignancy in lymph node invasion status and tumor metastasis." (PMID 38369634, 2024). "We found that only ATP6AP1, PSMD14 and HSP90AB1, were generally existent and highly expressed in tumor tissue (data not shown)." (PMID 38327651, 2023). "Then, we selected ATP6AP1, PSMD14 and HSP90AB1 as the candidate genes and verified the expressions in 63 cases of tumor tissues and the adjacent non-tumor tissues." (PMID 38327651, 2023). "However, the IHC results of SLC25A3 protein between normal and HCC tumor tissues were not existed in HPA, besides the obvious trend differences of ATP7A and ATP6AP1 expression in HCC patients were difficult to show in the HPA database." (PMID 36313717, 2022).
cancer (17 papers, 2016 to 2025). A tumor composed of atypical neoplastic, often pleomorphic cells that invade other tissues. "ATP6AP1 depletion disrupted autolysosome formation or function, leading to reduced autophagic flux and rendering cancer cells more susceptible to DOX-induced cell death." (PMID 39627767, 2024). "Recent studies showed that ATP6AP1 plays a crucial role in some cancers, and its mutation can contribute to malignant growth and cancer development." (PMID 38369634, 2024). "Expression of CA-Rheb in these cells could restore migration in wound healing, transwell migration/invasion, and proliferation assays, suggesting that the effects of ATP6AP1 deficiency on cancer cell growth and migration were indeed dependent on Rheb activity." (PMID 38448650, 2024). "Furthermore, the analysis demonstrated ATP6AP1 expression was correlated with the infiltration of immune cells and cancer-associated fibroblasts in the microenvironment of CRC." (PMID 38369634, 2024). "To explore the biological function of ATP6AP1 in pan-cancer, especially CRC, we performed a series of bioinformatics analyses." (PMID 38369634, 2024). "In TCGA data, differential ATP6AP1 expression was significant among 19 of the 33 cancer types analyzed, including 14 upregulation and 5 downregulation." (PMID 38369634, 2024). "Loss-of-function mutations of the assembly factor genes are associated with a spectrum of disease symptoms, and the normal function of CCDC115, ATP6AP1, and ATP6AP2 is associated with favorable phenotypes in several cancer types." (PMID 33680927, 2020). "Three (CCDC115, ATP6AP1 and ATP6AP2) of the five assembly factor genes are associated with several cancers." (PMID 33680927, 2020). "The role of ATP6AP1 in cancer is currently not well understood." (PMID 40133274, 2025). "In fact, targeting the ATP6AP1 C-tail could block Rheb activation and inhibit cancer cell proliferation and migration." (PMID 38448650, 2024). "Whether functional peptides and/or small molecules derived from ATP6AP1 can serve as specific inhibitors of mTORC1 pathways warrants further investigation that may yield therapeutic alternatives for cancer and disease treatment." (PMID 38448650, 2024). "However, when performing the analysis of matched ATP6AP1 mRNA expression using TCGA data, we found significant differences in 14 out of the 23 cancer types examined." (PMID 38369634, 2024). "Cancer occurrence and progression may be facilitated by aberrant expression of ATPase H+ transporting accessory protein 1 (ATP6AP1)." (PMID 36147483, 2022). "The interactions of cancer-related proteins with viruses may alter the prognoses of cancer patients; however, the effects of ATP6AP1 on the prognoses of BC patients during the COVID-19 pandemic have not been described." (PMID 34228637, 2021). "In contrast to the high frequency of likely inactivating ATP6AP1 (61%) and ATP6AP2 (11%) somatic mutations in the GCTs analyzed in this study, mutations affecting these genes were found in only 0.27% and 0.25% of common cancers, respectively." (PMID 30166553, 2018). "However, the function of ATP6AP1 in autophagy remains unknown, and the role of ATP6AP1 in cancer is still poorly understood." (PMID 40133274, 2025). "ACE2, RAB7A, CCDC22, ATP6AP1, NPC1, and PIK3C3 exhibited a positive relationship with sensitivity of 18 anti-cancer drugs (P < 0.01)." (PMID 35082790, 2021). "We found that ATP6AP1 levels were significantly greater in BC tissues than in normal breast tissues, and correlated significantly with the cancer stage and lymph node metastasis status (N1 vs. N0)." (PMID 34228637, 2021). "ACE2, RAB7A, PIK3C3, ATP6AP1, NPC1, and ATP6V1A had a negative association with the sensitivity of 16 anti-cancer drugs (P < 0.05)." (PMID 35082790, 2021).
cancer (continued). "Furthermore, 62.5% of SARS-CoV-2-required genes containing ACE2, TMPRSS2, ATP6AP1, ATP6V1A, and CCDC22 exhibited a significant upregulation in UCEC relative to normal tissue, while only PIK3C3 showed an obvious downregulation in this cancer." (PMID 35082790, 2021). "Importantly, however, the role of loss-of-function germline mutations affecting ATP6AP1 and ATP6AP2 remains to be determined and neither ATP6AP1 nor ATP6AP2 have been previously implicated in cancer." (PMID 30166553, 2018). "To determine whether ATP6AP1 and ATP6AP2 loss-of-function mutations are pathognomonic for GCTs, we investigated their presence in 6285 non-hypermutated cancers across 14 common cancer types from The Cancer Genome Atlas (TCGA) studies retrieved from the cBioPortal6." (PMID 30166553, 2018). "In this study, the expression of VMA21 was correlated with the expression of ATP6AP1 and ATP6AP2, although which were not differentially expressed between cancer and noncancer tissues." (PMID 33680927, 2020). "In this study, we identified VMA21 as the only candidate gene showing differential expression between cancer and noncancerous colorectal tissues among five known assembly factor genes (TMEM199, VMA21, CCDC115, ATP6AP1, and ATP6AP2) of the V0 domain." (PMID 33680927, 2020).
infection (6 papers, 2014 to 2025). The state of being infected such as from the introduction of a foreign agent such as serum, vaccine, antigenic substance or organism. "We found that the knock-down of four genes (DNM3, IDH3G, EPS15 and ATP6AP1) significantly inhibits HIV-1 replication, especially at later time-points (from four to seven days post-infection)." (PMID 25496667, 2014).
ATP6AP1 also shares sentences with these, for which no sentence is quoted: Cognitive impairment (6 papers); congenital disorder of glycosylation (2); diabetes (2); nematode infections (2); adrenal tumours (1); bacterial infections (1); cervical tumours (1); colon cancer (1); copper metabolism disorder (1); cutis laxa (1); cyst (1); deafness (1); dilated cardiomyopathy (1); glycosylation disorder (1); hearing loss (1); hematologic cancer (1); Hepatic steatosis (1); hepatitis B (1); hepatitis C (1); hepatocellular carcinoma (1); kidney chromophobe (1); leukemia (1); liver cancer (1); lung carcinoma (1); metabolic disease (1); neurological disease (1); oncocytomas (1); paraganglioma (1); schwannoma (1); sensorineural hearing loss (1).
A further 2 diseases each share a sentence with ATP6AP1 in 1 paper.